IRF3 (interferon regulatory factor 3)
Description:
Key transcriptional regulator of type I interferon (IFN)- dependent immune responses which plays a critical role in the innate immune response against DNA and RNA viruses. Regulates the transcription of type I IFN genes (IFN-alpha and IFN-beta) and IFN-stimulated genes (ISG) by binding to an interferon-stimulated response element (ISRE) in their promoters. Acts as a more potent activator of the IFN-beta (IFNB) gene than the IFN-alpha (IFNA) gene and plays a critical role in both the early and late phases of the IFNA/B gene induction. Found in an inactive form in the cytoplasm of uninfected cells and following viral infection, double-stranded RNA (dsRNA), or toll-like receptor (TLR) signaling, is phosphorylated by IKBKE and TBK1 kinases. This induces a conformational change, leading to its dimerization and nuclear localization and association with CREB binding protein (CREBBP) to form dsRNA-activated factor 1 (DRAF1), a complex which activates the transcription of the type I IFN and ISG genes. Can activate distinct gene expression programs in macrophages and can induce significant apoptosis in primary macrophages. In response to Sendai virus infection, is recruited by TOMM70:HSP90AA1 to mitochondrion and forms an apoptosis complex TOMM70:HSP90AA1:IRF3:BAX inducing apoptosis. Key transcription factor regulating the IFN response during SARS-CoV-2 infection.
Synonyms: IIAE7
Tractability: PROTAC: UniProt records ubiquitination sites on it; ubiquitination databases record sites on it; its protein half-life has been measured.
Target class: Transcription factor
Gene: Protein-coding gene on chromosome 19 (49,659,569 to 49,665,861, reverse strand). Ensembl gene ENSG00000126456.
Subcellular location: Cytoplasm; Nucleus; Mitochondrion
Subcellular location (Human Protein Atlas): Cytosol
Pathways (Reactome):
Immune System: Activation of IRF3, IRF7 mediated by TBK1, IKKε (IKBKE); DDX58/IFIH1-mediated induction of interferon-alpha/beta; IRF3 mediated activation of type 1 IFN; IRF3-mediated induction of type I IFN; ISG15 antiviral mechanism; Interferon alpha/beta signaling; Interferon gamma signaling; LRR FLII-interacting protein 1 (LRRFIP1) activates type I IFN production; Negative regulators of DDX58/IFIH1 signaling; Regulation of innate immune responses to cytosolic DNA; TICAM1-dependent activation of IRF3/IRF7; TRAF3-dependent IRF activation pathway; TRAF6 mediated IRF7 activation
Disease: Evasion by RSV of host interferon responses; SARS-CoV-1 activates/modulates innate immune responses; SARS-CoV-2 activates/modulates innate and adaptive immune responses
Gene Ontology:
Molecular function: DNA-binding transcription activator activity; DNA-binding transcription activator activity, RNA polymerase II-specific; DNA-binding transcription factor activity; DNA-binding transcription factor activity, RNA polymerase II-specific; identical protein binding; protein binding; protein domain specific binding; protein homodimerization activity; RNA polymerase II cis-regulatory region sequence-specific DNA binding; sequence-specific DNA binding; sequence-specific double-stranded DNA binding; DNA binding; DNA-binding transcription repressor activity, RNA polymerase II-specific; promoter-specific chromatin binding; transcription cis-regulatory region binding
Biological process: cellular response to virus; cytoplasmic pattern recognition receptor signaling pathway; positive regulation of interferon-beta production; positive regulation of transcription by RNA polymerase II; positive regulation of type I interferon production; regulation of apoptotic process; toll-like receptor 4 signaling pathway; TRIF-dependent toll-like receptor signaling pathway; apoptotic process; cGAS/STING signaling pathway; defense response to virus; DNA damage response; immune system process; macrophage apoptotic process; MDA-5 signaling pathway; positive regulation of cytokine production involved in inflammatory response; positive regulation of interferon-alpha production; regulation of transcription by RNA polymerase II; cell surface receptor signaling pathway; cellular response to exogenous dsRNA; innate immune response; negative regulation of transcription by RNA polymerase II; positive regulation of canonical NF-kappaB signal transduction; positive regulation of cytokine production; positive regulation of DNA-templated transcription; and 4 more
Cellular component: chromatin; cytoplasm; cytosol; mitochondrion; nucleus; nucleoplasm
Genetic constraint (gnomAD): Loss-of-function variants: 31 observed, 44.09 expected, observed/expected ratio (o/e) 0.7, 90% interval 0.53 to 0.95. The upper end of that interval is the gene's LOEUF score, 0.95, which puts it in group 4 of 6, group 1 being the genes least tolerant of losing a copy. Missense variants: 505 observed, 564.47 expected, observed/expected ratio (o/e) 0.89, 90% interval 0.83 to 0.96. Synonymous variants: 228 observed, 235.85 expected, observed/expected ratio (o/e) 0.97, 90% interval 0.87 to 1.08.
Homologues: Orthologues: macaque IRF3 (94% identical), chimpanzee IRF3 (81% identical), dog IRF3 (77% identical), pig IRF3 (77% identical), rat Irf3 (74% identical), mouse Irf3 (70% identical), guinea pig IRF3 (67% identical), tropical clawed frog irf3 (32% identical), zebrafish irf3 (26% identical). Paralogues in human: IRF5 (31% identical), IRF6 (28% identical), IRF7 (27% identical), IRF4 (24% identical), IRF8 (23% identical), IRF9 (19% identical), IRF2 (14% identical), IRF1 (14% identical).
Diseases named in the same sentence as IRF3 in open-access papers:
IRF3 is named in the same sentence as 305 diseases in open-access papers, as found by Europe PMC text mining. Sharing a sentence is not in itself a finding about the gene and the disease. The quoted sentences say what the papers report.
viral infection (725 papers, 2007 to 2026). "When viral infection occurs, DNA-PK is activated to bind and phosphorylate the Thr135 site of IRF-3, reducing protein degradation caused by IRF-3 translocation to the cytoplasm and prolonging the half-life of IRF-3." (PMID 40038612, 2025). "Our findings provide new insights into the molecular mechanisms underlying viral infection-triggered IRF3 stabilization and activation." (PMID 39702801, 2025). "In general, virus infection and exposure to PAMPs and DAMPs result in the activation of interferon-regulatory factor 3 (IRF3), which causes the induction of IFN-I and IFN-stimulated genes (ISGs)." (PMID 38672110, 2024). "H2S has been shown previously to reduce activation of IRF3 and associated inflammatory responses to viral infection." (PMID 38889788, 2024). "Disruption of Egln1 in mice and zebrafish attenuates host innate antiviral immune responses, and Irf3 prolyl hydroxylation-deficient mice are more susceptible to lethal viral infections." (PMID 38670937, 2024). "Taken together, these data indicate that D2HG’s effects on DNMT1 and IRF3/7 that render IDH1mut glioma cells susceptible to virus infection." (PMID 37880243, 2023). "IRF3 is antiviral against a wide range of viruses; IRF3 deficiency causes increased viral replication and susceptibility to viral infection." (PMID 37515265, 2023). "In contrast, in vivo studies have reported inconsistent consequences of Irf3 deficiency between viral infections." (PMID 37733807, 2023). "Endogenous coimmunoprecipitation experiments indicated that viral infection induced association of IRF3 with SRC, and P4 treatment further enhanced their association." (PMID 35468896, 2022). "G3BP1 potentiates the RIG-I-related pathway via RNF125-mediated K48-linked polyubiquitination in response to viral infection, which results in IRF3 phosphorylation and increased IFN-β transcription." (PMID 35652658, 2022). "Firstly, either PGR- or SRC-deficiency impaired progesterone-triggered potentiation of IRF3 activation and antiviral gene expression following viral infection." (PMID 35468896, 2022). "TRIM26, a member of the tripartite motif (TRIM) protein family, composed of more than 70 members in humans, binds to IRF3 and transfers to the nucleus after virus infection to advance the K48-linked-polyubiquitin degradation of IRF3 in the nucleus." (PMID 35196784, 2022). "Results showed that the levels of p-TBK1 and p-IRF3 were reduced in GSNOR-deficient cells compared to WT cells after viral infection." (PMID 34678655, 2021). "Virus infection causes the activation of IRF3 to transcribe type-I interferon (e.g., IFNβ), which is responsible for inducing the interferon-stimulated genes (ISGs), which act at specific stages to limit virus replication." (PMID 33805458, 2021). "The roles of both Pin1 and MEKK2 in their unique suppression of the IRF3 pathway demonstrate possible mechanisms by which cancer cells promote greater susceptibility to viral infection." (PMID 33805458, 2021). "TLR3, which is mainly distributed in endosomes and recognizes double-stranded RNA (dsRNA) associated with viral infection, induces activation of interferon regulatory factor 3 (IRF3) and NF-κB." (PMID 34360632, 2021). "IRF3 plays a key role in regulating the innate response against viral infection and IRF3 splicing variants have been reported to affect that ability of IRF3 to trigger the expression of type I interferons and the interferon-stimulated genes in infected cells." (PMID 31046669, 2019). "PINK1 positively regulates the antiviral immune response through enhanced association with TRAF3 and IRF3 upon virus infection, which promotes IRF3 phosphorylation and results in increased IFN-β and IL-6 transcription." (PMID 31139191, 2019). "The IRF3/IRF7 heterodimer is widely implicated in viral infection, inflammatory diseases and plays an important role in promoting septic shock." (PMID 31178872, 2019).
viral infection (continued). "Brd3 interacts with both IRF3 and p300, increases p300-mediated acetylation of IRF3, and enhances the association of IRF3 with p300 upon virus infection." (PMID 28045112, 2017). "Viral infection activates IRF3 by causing phosphorylation of its specific serine residues and its translocation to the nucleus, where it binds to the promoters of the target genes." (PMID 28824886, 2017). "It is known that upon viral infection, IRF3 is phosphorylated, exposing the IRF association domain at the C-terminus." (PMID 28955326, 2017). "Western blot analysis of cytoplasmic fraction and nuclear fraction showed that more IRF3 was translocated into nucleus in macrophages from WT mice compared to that from OPN-deficient (Spp1−/−) mice after virus infection." (PMID 27026194, 2016). "The importance of IRF3 in the development of antiviral immunity has been shown by using IRF3-deficient animals, which are more susceptible to viral infection." (PMID 25069698, 2014). "IRF-3 and NF-κB act as molecular sensors that respond to a wide variety of changes in the environment, including those caused by viral infection." (PMID 24034559, 2013). "TBK1 and IKKi are conjugated with Lys63-linked polyubiquitin chains during virus infection as a mechanism to promote IRF3 activation." (PMID 23308279, 2013). "TBK1 and IKKi both undergo Lys63-linked polyubiquitination following virus infection, presumably to recruit a signaling complex containing ubiquitin binding proteins that activate IRF3." (PMID 23308279, 2013). "At early times (6–12 h after virus infection), promoter occupancy by IRF3 and IRF7 is associated with transient recruitment of GCN5 and virus-induced histone H3K9 and H3K14 acetylation of IFN-A gene promoters." (PMID 22685561, 2012). "When IFN-β-signalling was disrupted by the use of macrophages from mice deficient in the IFN I receptor (IFNAR) there was again protection against apoptosis induced by viral infection to a similar extent as by the loss of Noxa or IRF-3." (PMID 21698224, 2011). "Third, Vero E6-encoded interferon regulatory factor 3 (IRF3), a transcription factor necessary for generating responses to virus infection, is relatively inefficient, resulting in a muted initial response to virus infection." (PMID 20567522, 2010). "Because MEF have been studied extensively in virus infection-host immune response assays, we initially evaluated the effect of an IRF-3 × IRF-7 deficiency in these cells." (PMID 19798431, 2009). "This implies that SVCV-P, along with its associated TBK1 and IRF3 complexes, might be targeted for autophagic degradation during viral infection, as aggregated proteins are frequently cleared by this pathway (39, –, 41)." (PMID 41363845, 2026). "Notably, viral-infection-induced downregulation of MALAT1 expression has been associated with enhanced activation of IRF3 and production of type I IFNs, suggesting its antiviral role in therapy." (PMID 39940816, 2025). "In addition, the K63-linked ubiquitination has been identified as an IRF3 activator during viral infection." (PMID 39761299, 2025). "IRF3 is a key transcriptional factor implicated in the innate immune response to viral infections." (PMID 38227600, 2024). "Furthermore, mice and zebrafish with Egln1 deletion, treatment with the EGLN inhibitor FG4592, or mice carrying an Irf3 P10A mutation are more susceptible to viral infections." (PMID 38670937, 2024). "Furthermore, OUT deubiquitinase 7B (OTUD7B) promotes autophagic degradation of IRF3 upon viral infection by enhancing the association between IRF3 and p62, thereby negatively regulating the immune response." (PMID 38660307, 2024). "IRF3 deficiency causes detrimental effects to the host during virus infection." (PMID 36507301, 2022). "Moreover, the activated caspase-3 can cleave cGAS, mitochondrial antiviral signaling protein (MAVS), and IRF3 to prevent the production of IFN-I during virus infection-caused apoptosis." (PMID 36189363, 2022).
viral infection (continued). "In general, sensing of viral infection in epithelial cells by cytosolic innate immune receptors leads to the parallel activation (i.e., phosphorylation) and nuclear accumulation of the two hallmark transcription factors IRF3 and NF-κB." (PMID 35022513, 2022). "Moreover, upon viral infection, the transcription factor IRF3 (interferon regulatory factor 3) is modified with K6-linked conjugates, which stimulates it to induce immune gene expression." (PMID 35880291, 2022). "Moreover, OTUD1 removes viral infection-induced K6-linked ubiquitin moieties from IRF3, resulting in dissociation of IRF3 from the promoter region of its target genes without affecting its protein stability, dimerization, or nuclear translocation." (PMID 34782737, 2021). "In addition, the IRF family contains various subtypes, of which IRF3 is associated with host defenses against viral infections." (PMID 30679658, 2019). "As TBK1 has been implicated in IRF3 activation in response to viral infections, we then test whether TBK1 is involved in IRF3 activation, thus leading to type I IFN production following infection with IAV." (PMID 29312300, 2017). "Previous studies have linked IRF3 activation to Bax-mediated apoptosis during viral infection." (PMID 27935834, 2016). "Viral infection induces large-prion like MAVS aggregates implicated in IRF3 activation." (PMID 23028469, 2012). "Hence, Irf3 knockout mice exhibit substantially increased susceptibility to viral infection." (PMID 30232186, 2018). "IRF3 regulates the Type I interferon response that prevents/limits virus infections, and STING can also promote neointima formation via proliferation, migration, and phenotypic switching in VSMCs through NF-kB signalling." (PMID 40493738, 2025). "DYRK4 acts as a scaffold protein to recruit TRIM71 to interact with IRF3, increasing IRF3 linear ubiquitination, maintaining IRF3 stability during viral infection, and promoting IRF3-mediated antiviral responses." (PMID 39702801, 2025). "In viral infections, the IRF-3 mediated signaling pathway is widely recognized for its pivotal role in inducing the expression of type I interferon." (PMID 41157636, 2025). "The resultant TDP35 enhances nuclear IRF3 levels by degrading Rbck1 pre-mRNA, thus averting the proteasomal degradation of IRF3 during viral infection and selectively promoting antiviral IFN-I production." (PMID 40006907, 2025). "Viral infections have been noted to induce OTUD4 expression via IRF3/7, which subsequently binds to mitochondrial antiviral signaling protein (MAVS), inhibiting its ubiquitination." (PMID 40277358, 2025). "NF-κB and IRF3 (Interferon Regulatory Factor 3) are key players in the innate immune response, particularly in response to viral infections, where they promote the Th1 response." (PMID 40432048, 2025). "Following virus infection, we observed the restoration of IRF3 phosphorylation and IFNB mRNA expression in cells complemented with TBK1, with further enhancement upon Frk overexpression." (PMID 40012791, 2025). "For example, YAP1 inhibits the production of type I IFN by interacting with IRF3, blocking its dimerization and nuclear translocation, thereby preventing IRF3-mediated type I IFN expression in response to viral infection." (PMID 40784457, 2025). "IRF3 is constitutively expressed in cells, providing a rapid response mechanism for cells to counter viral infections." (PMID 40245000, 2025). "Since the interaction between DYRK4 and IRF3 depends on viral infection, DYRK4 affects IRF3 ubiquitination during viral infection." (PMID 39702801, 2025). "Endogenous coimmunoprecipitation experiments revealed that DYRK4 was constitutively associated with IRF3 in uninfected cells and that the interaction between DYRK4 and IRF3 increased to high levels at 8 and 12 h of viral infection." (PMID 39702801, 2025).